IL1B (interleukin 1 beta)
Diseases named in the same sentence as IL1B in open-access papers (continued):
Sharing a sentence is not in itself a finding about the gene and the disease.
atherosclerosis (continued). "Furthermore, the extract also restrained the levels of the local inflammatory cytokines IL-1β and IL-6, suggesting that fistular onion stalk extract may be helpful for the attenuation of atherosclerosis." (PMID 29038791, 2017). "Thus, diacerein may reverse IL-1α’s effects on atherosclerosis and also reduce its expression by ECs via suppressing IL-1β activity." (PMID 28323859, 2017). "Lastly, mice with NLRP3 or IL-1β deficiency in bone marrow cells develop less inflammation and atherosclerosis under hypercholesterolemic conditions, supporting the correlation between activation of the NLRP3 inflammasome in macrophages and development of atherosclerosis." (PMID 28729463, 2017). "Together, these results show a role for CD36/SR-B2 at multiple points in Pg mediated enhanced atherosclerosis, and support the hypothesis that TLR-CD36/SR-B2 mediated IL1β generation, leading to increased foam cell formation, may be essential to the enhancement in atherosclerosis lesion observed." (PMID 25938460, 2015). "However, given the well-documented role for IL-1β in inflammation and atherosclerosis combined with the known role for GzmA in the production of this cytokine and others, it is plausible that GzmA could be contributing to atherogenesisas well." (PMID 24205352, 2013). "The increase in macrophage-derived TNF-α and IL-1β in the circulation during periodontitis also supports the idea that chronic periodontitis is involved in the pathogenesis of systemic inflammatory diseases, including atherosclerosis, cardiovascular disease, and diabetes." (PMID 24363500, 2013). "The expression of vascular inflammatory markers was assessed to further determine whether the elevation of SREBP-1 and NLRP3- and ASC-mediated production of IL-1β is pathologically relevant to vascular inflammatory process and endothelial dysfunction in atherosclerosis." (PMID 23825667, 2013). "Additionally, both IL1β and IL1α contribute to the pathogenesis of experimental atherosclerosis." (PMID 21698167, 2011). "Our results indicate that the activation of CD14, TLR4, and TLR2 on monocytes and macrophages by a very early form of oxidized LDL induces the secretion of pro-inflammatory cytokines such as IL-1β and IL-6, which may contribute to or exacerbate inflammatory responses during atherosclerosis." (PMID 20946675, 2010). "These mutant cells exhibit amplified IL-1β production, enhanced NLRP3-inflammasome activity, and increased chemokine signalling, thereby accelerating atherosclerosis, insulin resistance, and vascular inflammation." (PMID 41665140, 2026). "The central role of inflammation in atherosclerosis was further established by the CANTOS trial (Canakinumab Anti-inflammatory Thrombosis Outcome Study), which demonstrated that targeted inhibition of IL-1β significantly reduced cardiovascular events 59-61." (PMID 41424849, 2026). "Treatment with DNase I decreased NET formation and ameliorated atherosclerosis in ApoE−/−PAD4 KO mice, reducing levels of IL-1β, TNFα, CCL2, CXCL1, and CXCL2 under both in vitro and in vivo conditions." (PMID 40786884, 2025). "In a TET-2 mutated CH model, for example, monocyte-macrophages are activated with up-regulation of IL-1β signaling, mediated by the activated NLRP3 inflammasome, accelerating atherosclerosis development and maladaptive cardiac remodeling in mice." (PMID 40355940, 2025). "The NLRP3 inflammasome–IL-1β axis plays a particularly critical role in atherosclerosis (AS), where oxidized low-density lipoprotein (oxLDL) activates NLRP3, leading to IL-1β release, plaque instability, and thrombosis." (PMID 41394800, 2025). "While, we observed an obvious downregulation of pro-inflammatory markers (Il1b, Tnfa, Nos2) after Kdm2a knockdown after ox-LDL stimulation, which revealed the specific role of KDM2A in macrophages during atherosclerosis." (PMID 40303308, 2025).
atherosclerosis (continued). "This, in turn, triggers macrophage inflammation via the secretion of pro-inflammatory cytokines, such as IL-1β, IL-6, and TNF-α, thus promoting atherosclerosis." (PMID 39898976, 2025). "Ginger has been shown to inhibit the expression of pro-inflammatory mediators, such as TNF-α, IL-1β, and monocyte MCP-1, which play crucial roles in the development and progression of atherosclerosis." (PMID 39941147, 2025). "For instance, mice with TET2 knockout bone marrow transplants showed accelerated atherosclerosis, activated through the NLRP-3/IL-1β inflammasome pathway and upstream IL-6 signaling." (PMID 40355940, 2025). "IL-1β and MCP-1 regulate VSMCs phenotypic transition and MMP production, with MMPs playing a key role in VSMCs growth and atherosclerosis." (PMID 40283988, 2025). "Inflammatory response plays an important role in the progression of atherosclerosis, and TNF-α, IL-6, and IL-1β pro-inflammatory factors tend to induce the development of AS by destroying the vascular endothelium and increasing lipid deposition." (PMID 40606622, 2025). "Curcumin has been shown to inhibit the expression of pro-inflammatory mediators, such as C-reactive protein (CRP), TNF-α, IL-1β, and intercellular adhesion molecule-1 (ICAM-1), which play crucial roles in the development and progression of atherosclerosis." (PMID 39941147, 2025). "As expected, doxorubicin induced mitochondrial dysfunction, activation of NF-κB, and upregulation of proinflammatory cytokines (e.g., IL-6, IL-1β, and TNF-α) in HUVECs, triggering EndMT, a crucial process in the initiation and progression of atherosclerosis." (PMID 39851526, 2025). "Chronic H. pylori infection contributes to atherosclerosis by promoting systemic inflammation through cytokines such as TNF-α, interleukin-6 (IL-6), and interleukin-1 beta (IL-1β)." (PMID 40893911, 2025). "Our results showed that ox-LDL and IL-1β stimulation upregulated ALKBH5 in HCAECs, suggesting a role for this factor in regulating ECs function and angiogenesis in atherosclerosis." (PMID 40225569, 2025). "For example, in a mouse model of atherosclerosis induced by a HFD, the protein levels of NLRP3, ASC, GSDMD-N, IL-1β, and IL-18 were significantly elevated; GSDMD-mediated pyroptosis then accelerated the progression of atherosclerosis." (PMID 41194915, 2025). "Il1b serves as a key pro-inflammatory mediator in various chronic conditions, particularly in metabolic disorders, including T2DM, atherosclerosis, and non-alcoholic fatty liver disease." (PMID 41019552, 2025). "Pro-inflammatory cytokines (e.g., IL-1β, TNF-α) and growth factors released by activated neutrophils and platelets can promote endothelial dysfunction, atherosclerosis and cardiac remodeling." (PMID 41348675, 2025). "For example, in atherosclerosis, impaired CMA function leads to increased NOD-like receptor family pyrin domain containing three inflammasome activation and IL-1β secretion, promoting vascular inflammation and disease progression." (PMID 40873769, 2025). "Notably, targeting IL-1β with the monoclonal antibody canakinumab reduces cardiovascular events in patients with ASCVD, demonstrating a direct link between inflammation and atherosclerosis." (PMID 38753254, 2024). "TET2 LOF appears to promote atherosclerosis primarily via enhanced transcription and NLRP3-mediated posttranslational processing of the inflammatory cytokine IL-1β." (PMID 39352379, 2024). "STAT1 activation in endothelial cells upregulated the expression of inflammatory factor IL-1β and chemokine CX3CL1, triggering atherosclerosis progression." (PMID 38315275, 2024). "Factors such as lipopolysaccharide, oxidized LDL, TNF-α, and IL-1β have been noted for inducing PCSK9 secretion in various organs, contributing to conditions like hyperlipidemia, atherosclerosis, diabetes, and hypertension." (PMID 38762465, 2024). "In atherosclerosis, MMPs are upregulated in response to inflammatory cytokines, such as TNF-α, IL-1β, and IFN-γ." (PMID 39596083, 2024).
atherosclerosis (continued). "CMA function becomes impaired in atherosclerosis progression, leading to NLRP3 inflammasome activation and IL-1β secretion and promoting vascular inflammation and atherosclerosis progression." (PMID 39119608, 2024). "Previous studies have reported that pro-inflammatory molecule IL-1β and ox-LDL can induce EndMT, thereby promoting the progression of atherosclerosis." (PMID 38424494, 2024). "IL-1β, IL-6, IL-17, TNF-α, and hs-CRP are involved in the pathogenesis of atherosclerosis, psoriasis, and RA." (PMID 38927529, 2024). "The purpose of these trials is to assess mRNA vaccines for their potential to lower pro-inflammatory cytokines such as IL-1β and TNF-α, which are known to promote plaque progression, as well as LDL-C, a major driver of atherosclerosis." (PMID 39712846, 2024). "Plaque macrophages increase the expression of proinflammatory cytokines such as IL-6, IL-1β, and TNF-α, which are the first-wave inflammatory cytokines that impact atherosclerosis substantially." (PMID 36536168, 2024). "APG can improve atherosclerosis by stimulating apoptosis of macrophages and downregulating the secretion of cytokines (TNF-α, IL-1β, and IL-6)." (PMID 39830346, 2024). "Trelagliptin inhibits IL-1β-induced MCP-1 expression in human aortic endothelial cells by inhibiting the NF-κB pathway, preventing monocyte infiltration during atherosclerosis." (PMID 38384297, 2024). "Existing research has demonstrated the pivotal roles of NLRP3 inflammasome, IL-1β, and TNF in atherosclerosis." (PMID 38322269, 2024). "In late-stage atherosclerosis, NLRP3 inflammasomes induce macrophage cell death by pyroptosis, releasing IL-1β, IL-18, and inflammatory lipids, which increase plaque size and vulnerability to vessel rupture." (PMID 38335214, 2024). "The increased expression of miR-155 in atherosclerosis, psoriasis, and RA and its correlation with TNF-α and IL-1β make it an interesting target for future research and a potential therapeutic target." (PMID 38927529, 2024). "Hence, IL-1β may serve as a potential therapeutic target in atherosclerosis." (PMID 39528464, 2024). "Another action is the indirect reduction of the activation of IL-1β and downstream in IL-6 and CRP, which are well-known mediators that activate macrophages and propagate atherosclerosis." (PMID 37374202, 2023). "We noted a significant upregulation between MYD88 and CCL20 (G60); IFNβ (G90); NF-kB, IL18 (G120); NF-kB, CCR2, IL1b, IL18 (GF120); and CCR2 (GR120) in the thoracic aorta during the inflammatory process of atherosclerosis." (PMID 37298199, 2023). "Earlier studies have shown a link between IL-1β and the ECS for inflammatory diseases other than atherosclerosis as well as neurological diseases." (PMID 36178662, 2023). "Antibodies against IL-1β (canakinumab, gevokizumab, LY2189) and IL-1 receptor antagonists (anakinra) represent potential therapeutics for T2DM and atherosclerosis and have already been tested successfully in human studies." (PMID 37239938, 2023). "Here, a non-genetic model was applied to characterize the role of IL-1α, IL-1β, and NLRP3 for the pathogenesis of atherosclerosis." (PMID 37701434, 2023). "Canakinumab, a monoclonal anti-IL-1β antibody, is currently approved for treating several forms of arthritis, CAPS, and FMF, and its efficacy in reducing cardiovascular events in atherosclerosis patients has been shown in the large CANTOS trial." (PMID 37443800, 2023). "Clinical research on the signaling pathways leading to atherosclerosis has suggested that components of NETosis evoke NLRP3 inflammasome activation, which releases the proinflammatory cytokines IL-1β and IL-18." (PMID 36851139, 2023). "Like the processes seen in atherosclerosis, nicotine upregulates ICAM-1 and VCAM-1, thereby recruiting leukocytes and activating the production of IL-1β by macrophages." (PMID 37476160, 2023).
atherosclerosis (continued). "The serum IL-1β, IL-6, and TNF-α levels were significantly reduced, whereas IL-10 was greatly increased in mice with early and advanced atherosclerosis after GLSP treatment." (PMID 36923537, 2023). "IL-1β is a well-known local and systemic contributor to cardiovascular inflammation, where the recent CANTOS clinical trial outcomes affirm IL-1β as an atherosclerosis-relevant inflammatory target." (PMID 38034389, 2023). "Pro-inflammatory cytokines, such as IL-6, IL-1β, MCP-1 and TNF-α, are involved in the pathogenesis of atherosclerosis through inducing inflammatory cascades in the heart." (PMID 38041095, 2023). "In atherosclerosis, microRNA binding directly to human RNA-binding protein (HuR) regulates the formation of IL-6, TNF-α, IL-1β, and myocardial fibrosis via fibroblast activation and expansion." (PMID 38203612, 2023). "Analysis of GSE71226 and GSE9128 expression data of atherosclerosis group revealed that VEGFA was downregulated, while MMP9 and IL-1β were upregulated." (PMID 37880698, 2023). "IL-1β is known to induce the expression of adhesion molecules such as ICAM and VCAM in vascular smooth muscles, thereby promoting atherosclerosis progression." (PMID 37520489, 2023). "One of the earliest steps of atherosclerosis is the recruitment of leukocytes by endothelial cells through the expression of adhesion molecules (such as ICAM-1 and VCAM-1) induced by IL-1β." (PMID 37476160, 2023). "To date, anti-inflammatory therapy in atherosclerosis has targeted the NLRP3 inflammasome and upstream links of the IL-1β/IL-6/CRP axis." (PMID 36768404, 2023). "Bioinformatic and correlation analyses of differentially expressed immune cells helped to identify CCL4, TLR2, IL1B, and PTPRC as hub genes in atherosclerosis formation and plaque progression." (PMID 35509837, 2022). "Increased fatty liver-induced proinflammatory cytokines such as IL-1β, IL-18, and TNF-α can affect the development of atherosclerosis." (PMID 36364718, 2022). "However, IL-1β may be the double-edged sword in atherosclerosis." (PMID 36456628, 2022). "This review suggests that TMP inhibits inflammation in atherosclerosis by modulating TLR4, IL-6, and IL-1β levels." (PMID 35500001, 2022). "Many cytokines including TNF-α, IL-1β, and MCP-1 are expressed in atherosclerotic plaques, which impact foam cell formation and the progression of atherosclerosis." (PMID 36387364, 2022). "Studies conducted in the early 2000s examined the effects of IL-1β and IL-18, downstream cytokines of the NLRP3 inflammasome, on atherosclerosis in mice." (PMID 36082127, 2022). "The importance of inflammation in atherosclerosis was confirmed in the CANTOS clinical trial, which showed that anti-inflammatory therapy focused on targeting interleukin 1β (IL-1β) significantly decreased the rate of cardiovascular events." (PMID 35563407, 2022). "The resultant inflammasome releases upstream inflammatory cytokines such as IL-1β that activate inflammatory cells and produce IL-6, which stimulates the production of CRP, amplifying the inflammatory cascade and promoting atherosclerosis." (PMID 36558530, 2022). "Genes such as FCN1, IL1B, and SERPINA3 are involved in immune cell infiltration and regulate atherosclerosis (AS) through ceRNA." (PMID 36686646, 2022). "Circulating proinflammatory cytokines such as IL-1β and TNF-α are involved in the process of atherosclerosis." (PMID 35215505, 2022). "It is worth noting that IL-1β mediates the activation of NLRP3 inflammasome and the pathogenesis of atherosclerosis." (PMID 36304814, 2022). "The increased inflammation cytokines, including IL-6, IL-1β, and TNF-α, are also the main characteristics of atherosclerosis." (PMID 36145277, 2022).
atherosclerosis (continued). "Based on the correlation criteria and correlation criteria value, CCL2, CCL4, TLR2, IL1B and PTPRC were identified as hub immune genes in atherosclerosis." (PMID 35509837, 2022). "Amelioration of atherosclerosis and HF in Tet2 depleted mice by pharmacological inhibition of the NLRP3 inflammasome (MCC950), followed by reduction of IL-1b further confirmed this functional concept." (PMID 36355225, 2022). "Similar to the pathological process of atherosclerosis, the initiation phase of CAVD involves chemotactic action mediated by cytokines such as TNFα, IL-1β, and IL-6 to activate and recruit immune cells to valve tissue." (PMID 36589450, 2022). "Taken together, these findings demonstrated that OLFR2 ligation aggravates atherosclerosis progression by triggering NLRP3 inflammasome activation and subsequent proinflammatory IL-1β release." (PMID 35864109, 2022). "Taken together, these studies highlight the important role of IL-1β and the NLRP3 inflammasome in atherosclerosis and mark them as possible targets for the development of new therapeutic strategies." (PMID 35890291, 2022). "Tilianin derived from TFDM ameliorates atherosclerosis by inhibiting the production of the NF-κB-dependent proinflammatory cytokines TNF-α and IL-1β via the inhibition of IκB kinase activity." (PMID 35955548, 2022). "Using immunofluorescence, expression of p-STAT3 was also repressed by IL-1β in CD68 + αSMA + cells, which were shown to accumulate in the plaque during atherosclerosis progression." (PMID 36456628, 2022). "The eight major genes upregulated in the carotid vessels (IL18, PDGFRA, IL17, LOX1, TLR4, MYF5, IL1B, and PDPN) were intimately involved in the pathologic progression of atherosclerosis and NIH." (PMID 35531433, 2022). "Thus, GsdmD may play role in Nlrp3 inflammasome mediated dampening of RCT and in promoting the progression of atherosclerosis, either by virtue of increasing IL-1β release from live inflamed immune cells or by promoting pyroptotic cell death in advanced atherosclerotic plaques." (PMID 34395445, 2021). "Many in vitro and in vivo studies have shown the role of IL-1 in atherosclerosis and CVD and have provided strong evidence that IL-1β is a potent pro-atherogenic factor." (PMID 32378144, 2021). "Although the incidence of atherosclerosis-related cardiovascular events has been clinically reduced by the use of anti-IL-1β therapy, as shown in several large-scale population cohort trials, the clinical effect of IL-1β inhibition on atherosclerotic vascular calcification remains unclear." (PMID 34803503, 2021). "Interesting results on the location of atherosclerosis and genetic variation in 9 SNP of such genes as TNF-alfa, IL-1b, IL-10, and TGF-b1 were obtained by pathomorphologists studying this phenomenon among Japanese patients." (PMID 33801199, 2021). "Here, we demonstrated that elevated Hcy inhibits the expression of miR‐195‐3p, which in turn enhances IL‐31 expression and thereby causes the secretion of macrophages pro‐inflammatory factors IL‐1β, IL‐6 and TNF‐α and accelerate atherosclerosis." (PMID 34592792, 2021). "The inflammatory responses in atherosclerosis are mainly developed through the NLRP3 inflammasome, interleukin‐1 beta (IL‐1β) and interleukin‐6 (IL‐6) inflammatory response axis and eventually lead to an increase in the C‐reactive protein (CRP)." (PMID 34312998, 2021). "Additionally, it could be shown that PCSK9 aggravates atherosclerosis in apolipoprotein-E deficient mice, which was associated with an increased expression of inflammatory cytokines such as TNF-α, IL-1β, IL-10, MCP-1, and IL-8 to directly facilitate the process of inflammation." (PMID 34884827, 2021). "Our study shows that the expression levels of CD45, IL-1β and TNF-α are significantly increased in human coronary atherosclerotic lesions, which indicates that inflammation plays an important role in atherosclerosis." (PMID 34320932, 2021).